GSK3B (glycogen synthase kinase 3 beta)
Diseases named in the same sentence as GSK3B in open-access papers (continued):
Sharing a sentence is not in itself a finding about the gene and the disease.
schizophrenia (92 papers, 2005 to 2026). A major psychotic disorder characterized by abnormalities in the perception or expression of reality. "Our results address this issue to some extent, as we found evidence of the association of GSK3-α and GSK3-β with important clinical characteristics such as duration of schizophrenia." (PMID 41283305, 2025). "The Akt/GSK3β/mTOR signaling pathway has a consistent multifaceted association with the pathophysiology of schizophrenia." (PMID 35757972, 2022). "Since GSK-3β overexpression has been linked with CNS diseases such as schizophrenia, REGγ-mediated regulation of GSK-3β is a likely mechanism through which REGγ affects the CNS." (PMID 35892577, 2022). "The activity of GSK3β is negatively regulated by Akt and by the Wnt signaling pathway (a pathway that has been linked to schizophrenia)." (PMID 35844244, 2022). "Alterations in the Akt/GSK3β signaling pathway have been associated with mood disorders and schizophrenia." (PMID 28240305, 2017). "Glycogen synthase kinase 3β (GSK3β) has been implicated in the pathophysiology of schizophrenia and the actions of antipsychotic drugs." (PMID 27043526, 2016). "This study thus adds to the converging evidence that GSK3β represents a pathogenic signaling pathway in schizophrenia and affective disorders." (PMID 26728762, 2016). "Glycogen synthase kinase 3β (GSK3β)-dependent signalling pathways have been implicated in the pathophysiology of schizophrenia and antipsychotic drug actions." (PMID 27043526, 2016). "Some studies have demonstrated an association between GSK-3β polymorphisms and diagnosis of schizophrenia." (PMID 26694375, 2015). "Studies implicated Akt and GSK3β signalling in the pathophysiology of neuropsychiatric disorders such as schizophrenia, bipolar disorder, and depression." (PMID 26162083, 2015). "On the other hand, GSK-3β overexpression in mice showed an electroretinogram anomaly similar to the finding in subjects with high genetic risk for schizophrenia." (PMID 26694375, 2015). "It is intriguing that Wnt1, Fz3 and GSK3β – major Wnt/β-catenin pathway signalling components – have also been associated with schizophrenia or susceptibility to schizophrenia." (PMID 22615875, 2012). "In conclusion, this study suggests that altered SIK1/CRTC2/CREB1 and TWIST1/PI3K/Akt/GSK3β signaling pathways mediated by miR-25-3p is very likely to be associated with schizophrenia, revealing potential targets for the treatment and clinical diagnosis of schizophrenia." (PMID 36744005, 2023). "Furthermore, altered Akt/GSK3β signaling was widely reported to be associated with schizophrenia; and, it was pointed out that GSK3β can be phosphorylated at Ser9 by TWIST1 through the activation of the PI3K/Akt (Ser473) signaling." (PMID 36744005, 2023). "In addition, two possible downstream pathways of miR-25-3p, including the SIK1/CRTC2/CREB1 and TWIST1/PI3K/Akt/GSK3β signaling pathways, were examined with the schizophrenic rat model to explore their potential associations with schizophrenia." (PMID 36744005, 2023). "Additionally, our research authenticates that ERVWE1 regulates the expression of brain derived neurotrophic factor (BDNF), one of schizophrenia risk gene, through glycogen synthase kinase 3β (GSK3β) phosphorylation at Ser9." (PMID 36680208, 2023). "Most of the dysregulated pathways and genes found in schizophrenia research can be linked to GSK3β." (PMID 35844244, 2022). "The Akt-GSK3β signaling pathway has been implicated in the pathophysiology of schizophrenia." (PMID 35625659, 2022). "Since M-channel dysfunction has been linked to schizophrenia, epilepsy, and bipolar disorder, neuronal hyperexcitability resulting from impaired GSK3β-dependent M-channel dysfunction is likely a common denominator in several neurological and psychiatric illnesses." (PMID 35457230, 2022).
schizophrenia (continued). "A recent study showed that increased GSK-3β activity early in development predisposes to altered synaptic plasticity, dendritic spine loss, and cognitive disability in a rat neurodevelopmental model of schizophrenia." (PMID 31191636, 2019). "Additionally, GSK-3β promoter polymorphism rs3755557 that results in a higher promoter activity is associated with schizophrenia in the Chinese population." (PMID 31191636, 2019). "Additionally, the micro-RNA that is the most significantly associated to schizophrenia Mir137 has been shown to inhibit the expression of the Fxr1 negative regulator Gsk3β by acting on the 3′UTR of the GSK3B mRNA." (PMID 30087606, 2018). "Interestingly, knockdown of H2A.Z.1, but not H2A.Z.2, led to altered expression of several candidate genes linked to psychiatric disorders such as autism and schizophrenia (Neurexin1, Shank3, CaMK2G, Vamp7, Gsk3b, Tuba8, Grm8, etc.)." (PMID 28856239, 2017). "The present study explored the in vivo effects of one-week oral administration of aripiprazole on the GSK3β-dependent signalling pathways in three brain regions that are associated with schizophrenia and the actions of antipsychotics, in comparison with haloperidol and bifeprunox." (PMID 27043526, 2016). "However, our results are aligned with those of Emamian and associates who reported decreased phosphorylation of GSK3B at Ser9 in peripheral lymphocytes and frontal cortex of individuals with schizophrenia, suggesting increased GSK3B activity." (PMID 24236287, 2013). "The glycogen synthase kinase-3β gene (GSK3B) codes for a serine/threonine kinase that phosphorylates various proteins, including tau, and has also been associated with risk for neurodegenerative disorders and schizophrenia." (PMID 23951236, 2013). "In vivo, cell proliferation in the adult dentate gyrus could be rescued by administration of a GSK-3β inhibitor, which also suppressed schizophrenia- and depression-like behaviors caused by DISC1 loss of function." (PMID 23805076, 2013). "Furthermore, we are unaware of any study linking DVL2 gene expression to psychosis or other major psychiatric disorders, although numerous studies have implicated GSK3B in the pathogenesis of schizophrenia as well as antipsychotic drug action." (PMID 24236287, 2013). "Consequently, GSK3β inhibitors in the mPFC cause reduced prepulse inhibition, which reflects a dysfunction in sensorimotor gating—a feature reported in patients with psychiatric disorders such as bipolar disorder and schizophrenia." (PMID 35457230, 2022). "It has been proposed that the Akt/GSK-3β signaling pathway might be involved in the pathogenesis of schizophrenia and in the expression of dopamine-associated behaviors, and that antipsychotic medication may may exert their beneficial effects, at least in part, by modulating this pathway." (PMID 32163506, 2020). "Association between the Gsk3β-Fxr1 pathway and glutamatergic signaling also suggests how it may contribute to emotional regulation in response to mood stabilizers, or in illnesses like mood disorders and schizophrenia." (PMID 29706865, 2018). "GSK3β polymorphisms might be involved in Parkinson's disorder and schizophrenia risk." (PMID 25522158, 2014). "For example, a decrease in AKT1 protein levels and levels of phosphorylation of GSK3β at Ser9 in the peripheral lymphocytes and brains of individuals with schizophrenia was reported." (PMID 41510670, 2026). "Increased expression of intracellular GSK3-α and GSK3-β was detected in schizophrenia patients with a disease duration of more than 5 years (p = 0.019 and p = 0.018)." (PMID 41283305, 2025). "Schizophrenia patients, compared to controls, have lower levels of Akt and decreased phosphorylation of GSK-3β in the brain and peripheral lymphocytes." (PMID 36983018, 2023). "Extensive studies have indicated decreased levels of GSK3α and GSK3β total protein in the lymphocytes of schizophrenia." (PMID 35062349, 2022).
schizophrenia (continued). "Data from the GSE25673 dataset indicated that GSK3β was significantly higher in schizophrenia than that in control (p ≤ 0.01)." (PMID 35062349, 2022). "Dopamine-associated neuropsychiatric illnesses, such as schizophrenia and bipolar disorder, seem to be characterized by impairments in the AKT/GSK3β pathway, while AKT/GSK3β-dependent signaling pathways are involved in the actions of antipsychotics." (PMID 35625659, 2022). "AKT1 down-stream targets, such as GSK3β, are also altered in schizophrenia, including a decreased level of GSK-3β protein phosphorylation and GSK-3β mRNA in the prefrontal cortex." (PMID 35625659, 2022). "In summary, our results provide novel insight on the peripheral hypofunction of the Akt/GSK3β/mTORC1 pathway, which has long been proposed as a point of convergence and etiological mechanism for schizophrenia." (PMID 35757972, 2022). "On the contrary, bioinformatics revealed that the mRNA levels of GSK3β were higher in schizophrenia." (PMID 35062349, 2022). "After the motor activity test, the brains from d-amphetamine-treated animals were collected and processed for measurements of endocannabinoids and activation of Akt/GSK3β, two molecular markers involved in the pathophysiology of schizophrenia." (PMID 32163506, 2020). "At the same time, convergent evidence shows that the expression of GSK-3β and its related signaling pathways have changed in individuals affected by schizophrenia." (PMID 32143671, 2020). "We demonstrated that GSK3β inhibition restores the in vivo cortical gamma oscillation and cognitive function in the mouse model of Grin1 hypofunction relevant to schizophrenia." (PMID 32859995, 2020). "Previous studies have found both reduced and unchanged protein expression of GSK3β in postmortem PFC from subjects with schizophrenia." (PMID 32265715, 2020). "The immunodensity of GSK3β was found unaltered in schizophrenia (C: 122% ± 8%; SZ: 119% ± 10%), and the antipsychotic treatment did not modify significantly the content of the protein (AP-F: 134% ± 14%; AP-T: 100% ± 12%)." (PMID 32265715, 2020). "Conversely, the protein levels of GSK3β in the frontal cortex and cerebrospinal fluid are lower in schizophrenia patients than in normal subjects." (PMID 30285728, 2018). "A wide range of evidence has identified reduced phosphorylation levels and elevated GSK3β protein levels in the brains of schizophrenic patients, indicating hyper-activity of GSK3β in schizophrenia." (PMID 27043526, 2016). "Changes in the state of constitutionally active GSK3β were considered as both pathogenetic factor and therapeutic means in bipolar disorder and schizophrenia." (PMID 25852508, 2015). "From a translational perspective, our data suggest GSK3β as a target for pharmacotherapy of disorders from the ADHD-mania-schizophrenia continuum." (PMID 25852508, 2015). "Furthermore, a systematic meta-analysis showed that rs334558, functional polymorphism in the GSK-3β promotor region, is associated with incidence of schizophrenia, and suggested that this SNP might be used for differential diagnosis between schizophrenia and bipolar disorder." (PMID 26694375, 2015). "GSK-3β has also been involved in the disrupted in schizophrenia 1 (DISC1)-mediated regulation of adult neurogenesis." (PMID 23805076, 2013). "As well as neurodegeneration, GSK-3β plays a key role in neurodevelopment and GSK3B polymorphisms have been associated with schizophrenia." (PMID 23951236, 2013). "The finding that GSK3β is involved in the habituation process is interesting, considering that many neurological diseases, such as Schizophrenia, have been described to show defects of habituation in a number of paradigms." (PMID 23658842, 2013). "We recently also reported that an mGluR2/3 agonist can directly regulate the expression of NMDA receptors through activation of GSK-3β in the MK-801 model of schizophrenia." (PMID 23593498, 2013).
schizophrenia (continued). "Another report suggested the enhanced GSK-3β activity was secondary to diminished phosphorylation by Akt, since there is decreased Akt expression in schizophrenia patients' brains." (PMID 20492734, 2010). "For example, expressions of β-catenin proteins decreased in the brains of schizophrenia patients, presumably due to aberrant regulation of β-catenin degradation mediated by activated GSK-3β." (PMID 20492734, 2010). "The analysis of literature data indicates a significant role of impaired functional activity of GSK-3β in the pathogenesis of schizophrenia and affective disorders and the possibility of using the kinase as a molecular target for the development of therapeutic strategies." (PMID 41283305, 2025). "However, regarding the level of PI3K, AKT, mTOR, GSK3-α and GSK3-β in peripheral mononuclear cells (PMCs), the results are contradictory, possibly due to the heterogeneity of schizophrenia." (PMID 41283305, 2025). "This study found that prenatal Poly I:C challenge led to an increased mRNA expression of AKT1, AKT3, and GSK3β in the DRN; therefore, our findings provided the first evidence in the DRN to support the proposition that alterations in AKT‐GSK3β signaling contribute to schizophrenia pathogenesis." (PMID 40562368, 2025). "Moreover, down-regulation of DKK proteins and GSK3β, both negative regulators of Wnt signaling, are genetically and pharmacologically connected to schizophrenia." (PMID 40377402, 2025). "Moreover, the duration of the disease has a significant effect on the expression of GSK3-α and GSK3-β in schizophrenia patients." (PMID 41283305, 2025). "Similarly, the mRNA expression of CTNNB1 and GSK3β remained unchanged in the DLPFC of patients with schizophrenia." (PMID 39061390, 2024). "This study investigated whether miR-25-3p-mediated SIK1/CRTC2/CREB1 and TWIST1/PI3K/Akt/GSK3β signaling pathways are present in an animal model relevant to schizophrenia." (PMID 36744005, 2023). "In conclusion, the present study suggests that miR-25-3p-mediated SIK1/CRTC2/CREB1 and TWIST1/PI3K/Akt/GSK3β signaling pathways could be potential therapeutic targets for future antipsychotic drugs and candidate diagnosis biomarkers of schizophrenia." (PMID 36744005, 2023). "Furthermore, the involvement of GSK3β in the pathophysiology of schizophrenia has been well-documented." (PMID 36744005, 2023). "One key transcript that presents in our dataset, GSK3β, is a central hub in AD and schizophrenia." (PMID 37461529, 2023). "GSK-3β inhibitors were developed to treat neurodegenerative diseases such as AD, PD, bipolar disorder, and schizophrenia, but the long-term use of these inhibitors might disrupt many cellular processes because GSK-3β is a constitutively active kinase." (PMID 35055183, 2022). "Additionally, among molecules related to the signaling pathway of PIs, the expression of Akt was significantly higher in patients with schizophrenia than in controls, but the expression of GSK3β was unchanged." (PMID 34361045, 2021). "GSK-3β plays a significant role in cognitive function of schizophrenia." (PMID 32143671, 2020). "The PI3K-Akt-GSK3β pathway is downregulated in schizophrenia." (PMID 33584282, 2020). "With that said, drugs that modulate GSK3β and Erk1/2 have shown significant promise in treating synaptic and behavioral defects of schizophrenia, depression, and bipolar disorder." (PMID 32431597, 2020). "Indeed, lower phosphorylated GSK-3β Ser9 levels were detected in platelets of patients with schizophrenia." (PMID 31191636, 2019). "New GSK3β inhibitors have been actively developed for brain diseases, which may pave the way for establishing new treatments for schizophrenia." (PMID 30285728, 2018). "Accumulating evidence suggests that the dysregulation of GSK3β and/or its up/downstream molecules may contribute to bipolar disorder and schizophrenia." (PMID 30285728, 2018).
schizophrenia (continued). "Interestingly, reducing GSK3β activity was able to correct behavioral deficits in DISC1 mutant mice, strongly implicating DISC1 affects GSK3β in schizophrenia pathogenesis." (PMID 23543703, 2013). "Moreover, the protein, mRNA and activity of GSK3β are reduced in the postmortem brains of Schizophrenia patients, suggesting the involvement of GSK3β activity in the etiology of schizophrenia." (PMID 23658842, 2013). "In addition, anomalous GSK3β signaling has been reported in psychiatric diseases, including bipolar disorder and schizophrenia." (PMID 20111716, 2010). "In addition, previous investigations have shown that in post-mortem tissues from individuals with schizophrenia the levels of GSK3β are decreased." (PMID 20111716, 2010). "However, it is known that the loss of disrupted in schizophrenia 1 (DISC1), a scaffold protein involved in synaptic development and neural migration, potentiates Wnt/β-catenin by inhibiting the destruction complex member GSK3β." (PMID 40377402, 2025). "Therefore, the present study further explored whether the TWIST1/Akt/PI3K/GSK3β signaling pathway is abnormally modulated in schizophrenia." (PMID 36744005, 2023). "Selective loss of GSK-3β in the forebrain pyramidal neurons produced anxiolytic (reduced anxiety) and pro-social effects, and loss of GSK-3β but not GSK-3α in GABAergic neurons, reversed gamma oscillation deficits and cognitive dysfunction in an NMDA hypofunction model related to schizophrenia." (PMID 33572709, 2021). "Therefore, the present study examined the different effects of one-week oral administration of aripiprazole on the Akt-GSK3β and Dvl-GSK3β-β-catenin signalling pathways in three schizophrenia-related brain regions in comparison with a D2R antagonist—haloperidol and a D2R partial agonist—bifeprunox." (PMID 27043526, 2016). "Therefore, our finding further indicates that inhibition of GSK3β function in the NAc may contribute to the effects of antipsychotics on the positive symptoms of schizophrenia." (PMID 27043526, 2016). "Dysregulation of GSK-3β and 3α is one of promising neurodevelopmental hypotheses of schizophrenia." (PMID 18702828, 2008). "This new mechanism is in agreement with observations showing altered Wnt pathway genes such as GSK3β, WIF1, as well as AKT1 in schizophrenia postmortem brains." (PMID 36131044, 2022). "In this context, a lower expression/density and activity of Akt and GSK3β has been described in the PFC of subjects with schizophrenia, although there are contradictory reports." (PMID 32265715, 2020). "In a dopamine transporter knockout mouse model of schizophrenia, acute treatment with PREGS was able to rescue behavioral anomalies through the NMDA receptor‐mediated AKT/GSK3β signaling pathway." (PMID 31347308, 2019). "As a result of disruptions that may occur in these pathways due to dysfunctions in the GSK-3β gene, neurological diseases such as AD, PD, Huntington disease, ALS, prion disease, spinocerebellar ataxia and schizophrenia may occur." (PMID 40520520, 2025). "Our earlier research revealed for the first time a novel connection between specific gene polymorphisms related to neuroplasticity and protein kinases (including MAPK, BDNF, GSK3β, and AKT1) and the development of schizophrenia symptoms that predict a poor disease outcome." (PMID 41283305, 2025). "For instance, studies examining WNT signaling genes in the prefrontal cortex of patients with schizophrenia reported no changes in protein expression for β-Catenin, GSK3β, and DVL2." (PMID 39061390, 2024). "Conversely, inhibition of GSK-3β by the selective inhibitor, BRD3731 (IC50 0.015 μM vs. 0.215 μM of β or α isoform respectively), reversed gamma oscillation and cognitive dysfunction in a mouse model of schizophrenia." (PMID 33572709, 2021).